ALMS1-IT1 (ALMS1 intronic transcript 1)
Gene: Long non-coding RNA gene on chromosome 2 (73,456,764 to 73,459,482, forward strand). Ensembl gene ENSG00000230002.
Diseases named in the same sentence as ALMS1-IT1 in open-access papers:
ALMS1-IT1 is named in the same sentence as 1 disease in open-access papers, as found by Europe PMC text mining. Sharing a sentence is not in itself a finding about the gene and the disease. The quoted sentences say what the papers report.
cancer (1 paper, 2022). A tumor composed of atypical neoplastic, often pleomorphic cells that invade other tissues. "Expression of long non-coding RNA (LncRNA) ALMS1 intronic transcript 1 (ALMS1-IT1) is observed in some cancer types, and we believe that it may have the potential to serve as a marker of COAD." (PMID 36281164, 2022).